IL10 (interleukin 10)
Diseases named in the same sentence as IL10 in open-access papers (continued):
Sharing a sentence is not in itself a finding about the gene and the disease.
infection (continued). "However, children with heavy S. haematobium infections had significantly higher GMI of urinary IL-6 (p < 0.001) and lower GMI of urinary IL-10 (p = 0.002) than children with light infections." (PMID 25223302, 2014). "We also examined whether IL-10-inducing chitin particles were released from fungal cells during infections." (PMID 24722226, 2014). "Additionally, some studies showed that different genotypes (1 and 2) of PRRSV were able to induce different patterns of IL-10 and TNF-a, which, therefore, caused different outcomes of the infection." (PMID 24992286, 2014). "However, in resistant mice, the cytokine profile switches to a type-2 response (IL4, IL10) during the late/chronic stages of infection, presumably restricting prolonged and exaggerated inflammatory responses." (PMID 25375156, 2014). "However, intermediate monocytes also show the highest expression of the anti-inflammatory cytokine IL-10 and are tolerant to stimulation during infection." (PMID 24490631, 2014). "Interestingly, at a later time point, CD4+CD25+CD127low/− iTreg cells contribute towards the enhanced suppression of effector cells in SbR-LD infection by generating more IL-10 and TGF-β." (PMID 25032977, 2014). "Therefore, we studied the involvement of TLR-2 receptor along with the CCR5 in the context of IL-10 production during the course of infection." (PMID 24695099, 2014). "We therefore asked whether IL-10 produced by CD4 T cells contributed to increased infection with S. Typhimurium." (PMID 24787713, 2014). "Infection of monocytes and monocyte-derived DCs with chlamydial serovars Ba, D and L2 could induce detectable secretion of cytokines IL-8, IL-6, IL-1β, IL-10 and TNF." (PMID 25123797, 2014). "After the occurrence of infection, elevated IL-10 plays the role of anti-inflammatory." (PMID 24887408, 2014). "Although IL-10 levels remained comparable to controls, the levels of IL-4 produced in alum + LAg immunized mice were significantly enhanced at 4 months post-challenge infection (p < 0.001)." (PMID 24428931, 2014). "To address this we here applied the gnotobiotic murine IL-10−/− infection model." (PMID 24587249, 2014). "Finally, elimination of infection resulted in significantly decreased frequencies of antigen – specific CD4+ T cells expressing IL-10, IL-19 and IL-24." (PMID 24699268, 2014). "Importantly, results from this and previous studies, suggest that IL-10 was critical for regulating inflammation during the acute stage of infection, while lipoxin A4 was important for immune regulation during chronic infection." (PMID 25352846, 2014). "Independently of several factors including initial inhalational injury severity, infection, and extent of surface burns, high early levels of IL-10 and low levels of IL-12p70 in the central airways are associated with ALI in patients intubated after acute burn/inhalation injury." (PMID 23691180, 2013). "At 90, 180 and 270 days post-infection there was an increase in IFN-γ production as well as IL-10." (PMID 23577121, 2013). "Furthermore, high percentages of DCs and macrophages, but also B cells, CD4+ and CD8+ T cells produce IL-10 nine and thirty days after Clone 13 infection when assessed in IL-10 reporter (VertX) mice." (PMID 24244162, 2013). "Interestingly, IFN-γ levels were maintained during infection whereas IL-10 concentration showed a progressive increase." (PMID 23577121, 2013). "This was consistent with the observation that PBMC from infected lambs released more IL-10 following stimulation with heat-inactivated ES antigen compared to PBMC obtained prior to infection, indicating that proliferating ES-antigen specific lymphocytes secreted IL-10." (PMID 23964850, 2013). "Furthermore, the activation of this cell population and the generation of IL-10 are normal during infection." (PMID 23800014, 2013).
infection (continued). "At 2 days after infection, the levels of IL-1, IL-6, TNF-α, and IL-10 were reduced; at 14 days after infection, the levels of IL-1, KC, TNF-α, and IFN-γ were reduced, and a reduction in the IL-6, KC, and IL-10 concentrations was observed at 28 days after infection." (PMID 23818746, 2013). "Because viral IL-10 is expressed earlier than human IL-10 following infection, it can efficiently prevent IFN-gamma-induced upregulation of primary (MHC-antigen complex) as well as costimulatory (B7, ICAM) signals in myeloid cells eventually impairing antiviral T-cell activation and inducing anergy." (PMID 23690819, 2013). "It is possible that during infection, the cellular source of IL-10 may dictate its cellular target and outcomes." (PMID 24386207, 2013). "Overall, st2−/− mice tended to have higher mediator levels in lungs than WT mice; especially 14 days after infection with influenza A modest but statistically significant differences were seen in pulmonary IL-6 (P<0.001), IL-1β (P<0.01), KC (P<0.05), IL-10 (P<0.05) and IL-33 (P<0.05) concentrations." (PMID 23483993, 2013). "When total specific Ig was measured in the course of infection, the early and elevated antibody response of IL-10−/− mice, and the crescent antibody production of WT mice could be observed." (PMID 24205424, 2013). "NK cells produced high amounts of IL-10 on a per cell basis on day 2 post infection." (PMID 24244162, 2013). "The up-regulation of HLA-G in trophoblast cells by IL-10 at later stages of infection may enhance effects of inhibitory receptors expressed on decidual NK cells." (PMID 23418570, 2013). "We assessed mRNA levels of several pro-inflammatory and anti-inflammatory (IL-10) cytokines and chemokines in the lungs of naïve and HkX-31 infected WT and Nox1−/y mice at early (i.e. Day 3) and later (i.e. Day 7) stages of the infection phase with quantitative real time PCR." (PMID 23577160, 2013). "Thus, IL-10 acts during the first two days after infection to prevent immunopathology and to establish viral chronicity." (PMID 24244162, 2013). "As the influence of IL-10 on the chronic phase of L. major infection and especially its role for sterile immunity has already been investigated before, we further concentrated on the effects of T cell-derived IL-10 on the activation of the immune system early after infection." (PMID 23825956, 2013). "Further studies are needed to address the kinetics of Tregs/IL-10 in the context of infections." (PMID 24386207, 2013). "While Il-10−/− mice were able to clear LCMV Clone 13 infection by day 12, Il-10fl/flxM5-Cre+ mice, harboring a mast cell specific IL-10 deficiency, were unable to control the infection akin their Cre negative littermate controls and C57BL/6 mice." (PMID 24244162, 2013). "Thus, CD4+Foxp3+ Treg cells appear to be the predominant T-cell source of IL-10 at the infection site, whereas in the LN IL-10 also emanates from CD4+Foxp3− Teff cells." (PMID 23319295, 2013). "Each combination of parameters yields ratios of average tissue concentrations ([TNF-α]/[IL-10]), which we plot against representative model outputs of total bacterial load, number of activated Mφs, and apoptosis of resting Mφs at 200 days post-infection." (PMID 23869227, 2013). "Indeed, IL-10 blockade in neonates is protective during both early and late infection, whereas this effect is only observed at early stage in adult mice." (PMID 23737810, 2013). "Our finding that disease progression is unaltered in the macrophage/neutrophil-specific IL-10 mutant mice, however, is in accordance with data showing that early after infection with L. major, secretion of IL-10 by neutrophils of C57BL/6 mice is higher than by neutrophils of susceptible BALB/c mice." (PMID 23825956, 2013). "Thus, DCs and monocytes/macrophages account for a significant proportion of IL-10 mRNA on day 2 post infection." (PMID 24244162, 2013).
infection (continued). "IL-10 regulates immune responses during many infections, predominantly by shifting immune responses towards a Th2-centric adaptive immune outcome that may benefit the host, and sometimes the pathogen." (PMID 24155979, 2013). "Neonatal mice also produced elevated levels of the cytokine IL-10 compared to adults upon infection with L. monocytogenes, and the survival-increasing and CFU-reducing benefits of IL-10 blockade were of substantially longer duration and of enhanced effect in neonates." (PMID 23653659, 2013). "One plausible explanation for lower levels of IL-12p70, IL-10, IL-1β, and GM-CSF may be attributed to differences in the time kinetics for their optimum secretion during the infection process." (PMID 23766556, 2013). "This increase in IL-10 level in macrophages in response to infection by the wild-type strain was associated with an absence of ROS and NO production." (PMID 24039915, 2013). "IL-10 is an immunomodulatory cytokine that is able to inhibit the synthesis and release of other cytokines, thereby inhibiting cell-mediated immunity and extending the duration of viremia in the peripheral blood during the early stage of infection." (PMID 23631691, 2013). "The IL-10-/- mouse is currently the only infection model where manipulation of a single soluble immune mediator can significantly enhance Bb clearance in multiple target tissues, thus there is great interest in better understanding the mechanisms affected during IL-10 suppression of Bb clearance." (PMID 24367705, 2013). "Since IL-10 secretion by CD4+ CD25+ FoxP3+ Treg cells as well as CD4+ CD25− FoxP3− Th1 cells has been implicated in the control of chronic infection with Leishmania, it was important to determine the T cell population secreting IL-10 early after infection." (PMID 23825956, 2013). "In each of these cases, the trafficking of Bb to LAMP-1-containing compartments by MØs was significantly suppressed by 30 min post-infection, and the suppression was lost in the presence of IL-10-blocking antibodies, confirming that the effects were IL-10-specific." (PMID 24367705, 2013). "However, one of the main features of K. rhinoscleromatis infection was the strong expression of IL-10, an anti-inflammatory cytokine with a crucial role in limiting the immune response during infection to pathogens and thereby preventing damage to the host." (PMID 23554169, 2013). "Interestingly, DCs also secrete the anti-inflammatory cytokine IL-10 in response to pathogen infection." (PMID 23667643, 2013). "Agonistic stimulators of TLR-4 or-9 were shown to suppress the course of autoimmune diseases, which may also explain why infection with salmonella triggered the expansion of IL-10-producing B-cells." (PMID 24381571, 2013). "Based on our described kinetics of IL-10 production and their presence as skin-resident cells, it is likely that MØs and DCs are a significant source of Bb-elicited IL-10 at these early times post-infection." (PMID 24367705, 2013). "DEX and NDV cooperatively increased IL-10 production at all time points after infection." (PMID 23667643, 2013). "An increase of IFN-γ and IL-10 levels was detected during infection." (PMID 23577121, 2013). "At weeks 8 and 16, IL-10-deficient mice had nearly cleared infection, suggesting that cytokine production was no longer required." (PMID 24205424, 2013). "Thus, IDO1, promptly induced in infection, is apparently required for local immunoregulation via IL-10+ Treg cells." (PMID 23853597, 2013). "Likewise, the production of the anti-inflammatory cytokine IL10 was relatively low at the early time of infection in the lethal strain-infected mice compared with that in other viruses infected mice." (PMID 23758678, 2013).
infection (continued). "The kinetics of the abbreviated neutrophil recruitment corresponds with the significant IL-10 production seen in skin tissues by 24h post-infection, and our findings demonstrating subsequent decreases in proinflammatory cytokines and neutrophil-attracting chemokines when IL-10 is blocked." (PMID 24367705, 2013). "In the mesenteric lymph node IL-10 mRNA expression peaked on day 3 post infection." (PMID 24244162, 2013). "Several cell types can produce IL-10 following infection with L. major." (PMID 23555256, 2013). "We observed a substantial increase in IL-10 expression by CD4+ T cells following infection." (PMID 23555256, 2013). "Do TNF-α and IL-10 processes also affect infection outcomes?" (PMID 23869227, 2013). "In order to assess cell populations producing high amounts of IL-10 on a population level instead of on a per cell basis, the percentages of different cell populations of the splenocytes were determined on days 2 and 5 post infection." (PMID 24244162, 2013). "Several studies have suggested that a balance of TNF-α and IL-10 may be necessary for controlling infection while at the same time preventing severe host tissue damage during Mtb infection." (PMID 23869227, 2013). "Thus, BALB/c mice develop an uncontrolled disease that occurs concomitantly with a dominant Th2 response, while BALB/c Il10−/− mice resolve their infections." (PMID 23555256, 2013). "Similarly, the infection of IL-10−/− mice with the intracellular parasite T. gondii leads to enhanced IL-12 production by APC, resulting in an overwhelming and lethal Th1 immune response." (PMID 23825956, 2013). "IL-10 production represents a potent autoregulatory feedback loop that protects against excessive inflammation and potential tissue destruction during proinflammatory Th1-driven immune responses in infections." (PMID 24069337, 2013). "Moreover, Brucella infection has been shown to induce IL-10 production by splenocytes in vitro and during intravenous in vivo infection." (PMID 23818855, 2013). "CD8− DCs and pDCs expressed IL-10 mRNA on day 2 post infection." (PMID 24244162, 2013). "This is supported by the data that the reduction of Tregs and IL-10 production in pDC depleted mice is correlated with histologic findings showing massive cellular infiltration and extensive tissue damage in their lungs after infection." (PMID 24386207, 2013). "Interestingly, we observed that IL-10 was still highly expressed after K. rhinoscleromatis infection, contrasting sharply with the basal expression level observed during the 5 days post-infection after Kp110 infection." (PMID 23554169, 2013). "Therefore, we utilized IL-10 transcriptional reporter mice to define the cells within the lesions that were making IL-10 at one week of infection." (PMID 23555256, 2013). "Importantly, they have been described as one of the cell types responding to IL-10 production in other infection models." (PMID 23818855, 2013). "This IL-10 response is rapid, as substantial production is seen by macrophages in vitro within 4-6h after co-culture and significant increases in IL-10 transcript levels are seen in skin tissues within 24h post-infection with a physiological dose of Bb." (PMID 24367705, 2013). "Moreover, pDC activation following Cpn infection enhanced CD4 Tregs/IL-10 production and mediated the regulation of T cell responses for optimal immunity against infection." (PMID 24386207, 2013). "Similarly, NK cell specific IL-10 deficiency had no positive impact on the LCMV-specific T cell response or viral control, even though high percentages of NK cells produced IL-10 at early time points after infection." (PMID 24244162, 2013). "Since IL-10 is a pro-inflammatory cytokine produced at the site of inflammation, increased IL-10 expression soon after infection in late infected mice might result in less IFN-γ and TNF-α production thereby reducing cholangiocyte damage." (PMID 23844248, 2013).
infection (continued). "Importantly, we observed that the anti-inflammatory cytokine IL-10 was highly produced after K. rhinoscleromatis infection, up to 61 times more than after Kp52.145 infection 5 days post-infection." (PMID 23554169, 2013). "Therefore, it is possible that patients with higher infection rates in monocytes induced higher production of IL-10, which in turn contributes to disease pathogenesis." (PMID 24040431, 2013). "Interestingly, we found that both primary and secondary infections with lpg2− L. major result in suppressed IL-10 response." (PMID 23776605, 2013). "IL-1alpha, IL-2, IL-10 and IL-13 mRNA levels increased similarly during infection in all groups." (PMID 24204622, 2013). "However, following infection the IL-10 came from both CD4+Foxp3− and CD4+ Foxp3+ T cells, and about 50% of the CD4+Foxp3− T cells producing IL-10 also produced IFN-γ." (PMID 23555256, 2013). "The percentage of IL-10 producing cells decreased throughout infection in both genotypes." (PMID 24205367, 2013). "In the present study, the role played by MCs in neutrophil recruitment in analyzed tissues may be attributed to the consequence of a reduction in the expressions of IL-4 or IL-10 at the site of the infection in infected mice with C48/80 treatment." (PMID 24146978, 2013). "However, the CFU analysis revealed that IL-10−/− mice were able to clear P. brasiliensis infection in livers and spleens after 16 and 8 weeks of infection, respectively." (PMID 24205424, 2013). "While treatment with IL-10 may be of significant aid in sterile (pathogen-free) inflammatory disorders, its use in inflammatory processes that arise from infections may represent a double edged sword." (PMID 24260222, 2013). "In this study we showed that the agsΔ mutants displayed a reduced virulence associated with an inhibition of germination in vivo and a reduction of the inflammatory response after 24 h infection (decreased TNFα and increased IL10 expressions and reduced recruitment of PMNs)." (PMID 24244155, 2013). "However, the levels of IL-10 were lower in the pEGFP/Ag85A-HA2 vaccinated group on day 2 after infection with S. aureus (P < 0.05)." (PMID 23369570, 2013). "Similarly, resting MØ produced equal amounts of IL-10 in response to the infection with wild-type Mtb or ΔkstD strain." (PMID 23425360, 2013). "At first glance, our data suggest that inhibition of IL-10 signaling would be beneficial to the host, since IL-10−/−, IL-10flox/CD4Cre and IL-10Rflox/LysMcre showed increased ability to control B. abortus infection at both acute and chronic stages of infection." (PMID 23818855, 2013). "Analysis on day 5 post infection revealed that CD8+ T cell depleted mice expressed similar overall levels of IL-10 mRNA as undepleted controls, while CD4+ T cell depleted, clodronate liposome treated mice and DC specific IL-10 knockout mice (Il-10fl/flxCD11c-Cre+ mice) exhibited reduced levels." (PMID 24244162, 2013). "In vivo infection with S. aureus caused significantly elevated production of TNF-α and IL-6 in the livers and blood of TLR2-deficient mice compared with those in WT mice, while the hepatic and serum levels of IL-10 decreased in these mice." (PMID 24058538, 2013). "The role of Interleukin-10 in infections is complex, it may exacerbate T-cell dysfunctions and microbial infections." (PMID 24381571, 2013). "Infection of mice with Leishmania parasites is known to induce secretion of IL-10 by neutrophils." (PMID 23825956, 2013). "In summary, this study has demonstrated that H. trogontum infection in IL-10−/− mice generates acute-on-chronic typhlocolitis, thus reconfirming that infection of IL-10−/− mice with H. trogontum produces a picture similar to that observed in IBD, particularly CD." (PMID 24027765, 2013). "The circumparasitic leucocytes produce mainly IL-10 at five months post-infection." (PMID 23555767, 2013).